CMTM6 (CKLF like MARVEL transmembrane domain containing 6)
Diseases named in the same sentence as CMTM6 in open-access papers (continued):
Sharing a sentence is not in itself a finding about the gene and the disease.
breast carcinoma (15 papers, 2019 to 2025). "In patients with trastuzumab-resistant breast cancer, increased expression of CMTM6 is associated with a worse prognosis." (PMID 37174034, 2023). "In breast cancer, circ_0067842 facilitates metastasis and immune evasion via the HuR/CMTM6/PD-L1 axis, with its expression levels correlating with aggressive phenotypes and worse clinical outcomes." (PMID 41438756, 2025). "Activation of the EMT process in breast cancer cells can upregulate the expression of CMTM6, which is an essential protein for the cell surface expression of PD-L1." (PMID 38223763, 2024). "Further analysis displayed that CMTM6 mRNA transcripts were detected in different subtypes of breast cancer tissues, and the relative levels of CMTM6 mRNA transcripts were slightly higher in luminal A and B subtypes than other subtypes." (PMID 36627608, 2023). "Here we report that the expression of CMTM6 positively correlates with the epithelial to mesenchymal transition (EMT) score in breast cancer cell lines and with the major EMT marker Vimentin in triple-negative breast cancers (TNBC)." (PMID 33803139, 2021). "Recently, the uncharacterized protein CMTM6 has been identified as a critical regulator of PD-L1 surface expression in several types of cancer cells, including breast cancer cells." (PMID 33803139, 2021). "Here, we reported that activating EMT process in breast cancer cells upregulates CMTM6, an essential protein required for cell surface expression of PD-L1." (PMID 33803139, 2021). "CMTM6 silencing in mesenchymal breast cancer cells partially decreased PD-L1 expression on their cell surface, while dual targeting of CMTM6 and CMTM7 significantly decreased PD-L1 in these cells." (PMID 33803139, 2021). "The mRNA expression levels of CMTM5 and CMTM7 were significantly downregulated while those of CMTM1 and CMTM6 were significantly upregulated in breast cancer tissues than in corresponding normal tissues." (PMID 31998718, 2019). "This discovery indicates the potential relationship among HER2, PD-L1, and CMTM6 in breast cancer." (PMID 37174034, 2023). "Breast cancer pathological classification, TNM stage, triple-negative breast cancer, and high expression of CMTM6 could be used as independent risk factors to judge the prognosis of patients." (PMID 35845949, 2022). "In addition, CMTM6 expression was associated with differentiation in lung cancer, with a better prognosis in OV, and significantly higher in triple-negative breast cancer (TNBC) than HER2-driven breast cancer." (PMID 36698778, 2022). "In breast cancer patients, the expression level of CMTM5 and CMTM7 is decreased, while the expression level of CMTM6 is increased." (PMID 38223763, 2024). "Collectively, these findings highlight that CMTM6 stabilizes HER2 protein, contributing to trastuzumab resistance and implicate CMTM6 as a potential prognostic marker and therapeutic target for overcoming trastuzumab resistance in HER2+ breast cancer." (PMID 36627608, 2023). "Recent studies have suggested a link between targeted-therapy resistance and CMTM6, as CMTM6 is highly expressed in HER2-positive breast cancer and is co-localized with HER2 on the surface of breast cancer cells." (PMID 37174034, 2023). "In vitro, CMTM6 knockdown inhibited the proliferation and migration of HER2+ breast cancer cells, and promoted their apoptosis, while CMTM6 overexpression reversed these effects." (PMID 36627608, 2023). "Two studies have shown that CMTM6 and VISTA were expressed in both TCs and ICs in colorectal cancer and breast cancer, respectively." (PMID 38136305, 2023). "A previous study found that the dual knockdown of CMTM6 and CMTM7 observably downregulated the expression of PD-L1 in the breast cancer cell line MCF-7Mes, indicating the potential role of CMTM7 in reflecting the anti-tumor activity of BRCA." (PMID 36568362, 2022).
breast carcinoma (continued). "We demonstrated that a considerable part of PD‐L1 that is overexpressed during the EMT process is regulated via CMTM6 and CMTM7 in breast cancer cells." (PMID 35575054, 2022). "Overall, this study provides new insights into the significant role of CMTM6 and CMTM7 in the regulation of PD-L1 surface expression in breast cancer cells undergoing EMT." (PMID 33803139, 2021). "In breast cancer tissues, the mRNA expression levels of only CMTM1, CMTM5, CMTM6, and CMTM7 were measured." (PMID 31998718, 2019). "In mesenchymal breast cancer cells, CMTM6 silencing decreases PD-L1 expression on the cell surface, while dual targeting of CMTM6 and CMTM7 significantly reduces PD-L1 expression, suggesting that CMTM-targeted molecular therapy can improve the prognosis of breast cancer patients." (PMID 38223763, 2024). "Finally, the effect of targeting CMTM6 and/or CMTM7 in breast cancer cells undergoing EMT on tumor development, metastasis, and T cell activity should be addressed." (PMID 35575054, 2022).
lung cancer (15 papers, 2019 to 2025). A malignant neoplasm involving the lung. "In summary, CMTM6 expression is associated with PD-L1 expression, as well as lung cancer histotypes and metastasis." (PMID 31646201, 2019). "Furthermore, we for the first time reported that CMTM6 express in a cohort of lung cancers, and it is associated with lung cancer histotypes, metastases." (PMID 31646201, 2019). "CMTM4 and CMTM6, which share 55% amino acid identity, are downregulated in clear cell renal cell carcinoma and lung cancer and act as tumor suppressors." (PMID 40179060, 2025). "In lung cancer patients, CMTM6 expression acts as a predictor of PD-1 inhibitor therapy; that is, patients with higher CMTM6 expression respond well to PD-1 inhibitors." (PMID 38223763, 2024). "According to the pRRophetic package, further analysis was conducted to evaluate the correlations between CMTM6 expression and nine types of lung cancer-related chemotherapy drugs." (PMID 36643629, 2023). "In lung cancer patients, CMTM6 acts as a predictor for programmed cell death 1 (PD-1) inhibitor therapy; i.e., patients with higher CMTM6 expression respond well to PD-1 inhibitors." (PMID 33434185, 2021). "The current study, for the first time, demonstrated that CMTM6 expression is correlated with lung cancer histotypes and inversely correlated with cancer metastases in clinical samples, supporting earlier reports in cellular models." (PMID 31646201, 2019). "The result indicated that CMTM6 expression is correlated with lung cancers histotypes (higher CMTM6 in NSCLC than that in SCLC, P < 0.05) and inversely correlated with lymph nodes metastases (Chi-square test, P < 0.001), but not with patients’ age and gender." (PMID 31646201, 2019). "CMTM6 and PD-L1 expression were analyzed in 81 lung cancer patient sample, and we observed that CMTM6 expression correlated with cancer histotypes and inversely correlated with cancer metastases, but not with patients’ age and gender." (PMID 31646201, 2019). "Although conflicting research on CMTM6 and lung cancer prognosis exists, our multivariate analyses identified CMTM6 expression as an independent predictor of overall survival, supported by an increased sample size aligning with Marian's animal experiments, reinforcing our research conclusions." (PMID 38495487, 2024). "Recent studies confirmed that in a variety of cancers, PD-L1 and CMTM6 are coexpressed, including gastric cancer, liver cancer, head and neck squamous cell carcinoma, and lung cancer." (PMID 36643629, 2023). "There is a correlation between the expression of CMTM6 and PD-L1 in lung cancer." (PMID 33818637, 2021). "After the observation of the expression of CMTM6 and PD-L1 in different types of cancers, we focused the rest of our study on lung cancers as PD-1/PD-L1 inhibitors are currently in the first line therapy for lung cancers." (PMID 31646201, 2019). "In lung cancer, CMTM6 is correlated with NSCLC subtype and inversely correlated with metastases." (PMID 31646201, 2019). "Here we tested the expression of CMTM6 and PD-L1 in 81 lung cancers from 4 different histotypes." (PMID 31646201, 2019). "While CKLF-like MARVEL transmembrane domain containing 6 (CMTM6)'s role in stabilizing PD-L1 and immune evasion within tumors is established, its expression in lung cancer tissue and adjacent macrophages remains uncertain." (PMID 38495487, 2024). "CMTM6 expression varied among lung cancer histological types, notably more pronounced in squamous cell carcinomas than adenocarcinomas." (PMID 38495487, 2024).
colorectal cancer (12 papers, 2021 to 2025). A primary or metastatic malignant neoplasm that affects the colon or rectum. "In addition, the co-expression of CMTM6 and PD-L1 is associated with an active immune microenvironment and a favorable prognosis in colorectal cancer, especially in patients receiving adjuvant chemotherapy." (PMID 36568362, 2022). "Patients with high expression of CMTM6 in macrophages can obtain the greatest benefit from PD-1/PD-L1 blockade in colorectal cancer and in NSCLC." (PMID 35958549, 2022). "We aimed to investigate the expression pattern of CMTM6 between mismatch repair-defective (dMMR) and mismatch repair-proficient (pMMR) colorectal cancer (CRC) tissues and assess its correlation with the response to PD-1/PD-L1 pathway blockade." (PMID 33818637, 2021). "CMTM6 is highly expressed and plays an important role in various tumors such as oral squamous cell carcinoma (OSCC) and colorectal cancer (CRC), however, its role in Glioblastoma multiforme (GBM) is unclear." (PMID 36698778, 2022). "A recent study indicates that CMTM6 is expressed on CD8+ T cells and CD163+ M2 macrophages in colorectal cancer tissues." (PMID 34680324, 2021).
gastric cancer (11 papers, 2020 to 2024). A primary or metastatic malignant neoplasm involving the stomach. "CMTM6 has a tumor-promoting effect and CMTM6 is associated with a poor prognosis, especiallyin gastric cancer and HNSCC." (PMID 35958549, 2022). "In addition, high CMTM6 expression is associated with poor prognosis in gastric cancer and with better prognosis in non-small cell lung cancer (NSCLC)." (PMID 36698778, 2022). "Recent studies have suggested that CMTM6 is coexpressed with PD-L1 in a variety of cancers and has been proven to be an independent prognostic factor of gastric cancer and liver cancer." (PMID 36643629, 2023). "In our 180-dot tissue array with gastric adenocarcinoma, we confirmed that a high protein level of CMTM6 was correlated with worse survival and the co-expression of CMTM6 enhanced the prognostic value of PD-L1 in gastric cancer." (PMID 34680324, 2021). "As CMTM6/4 regulates PD-L1 at the protein level, we investigated the prognostic value of the three molecules by multiplex immunofluorescence staining in gastric cancer tissue array." (PMID 34680324, 2021). "The expression levels of CMTM6 and PD-L1 were examined in 185 gastric cancer specimens using immunohistochemistry, quantitative real-time PCR and Western blot." (PMID 33509216, 2021). "High expression of CMTM6 was correlated with poor prognosis of gastric cancer patients (HR = 1.668; 95% CI = 1.032–2.695; P = 0.037)." (PMID 33509216, 2021). "The expression of CMTM6 was significantly related to the positive expression of PD-L1 in gastric cancer tissues (r = 0.186, P = 0.041)." (PMID 32874775, 2020). "The expression of CMTM6 was significantly related to the positive presence of PD-L1 in gastric cancer tissues (r = 0.186, P = 0.041)." (PMID 32874775, 2020). "The low- and high-expressions of CMTM6 in gastric cancer tissues were 46.7% (57/122) and 53.3% (65/122), respectively, and the negative and positive expressions of PD-L1 were 35 (28.7%) and 87 (71.3%), respectively." (PMID 32874775, 2020). "We detected the expression of CMTM6 and PD-L1in 122 gastric cancer tissues using an IHC assay." (PMID 32874775, 2020). "Comparable results were shown in gastric cancer, where co-expression of FOXP3 and CMTM6 was related to a favorable prognosis." (PMID 38067301, 2023). "Interestingly, it was shown that co-expression of CMTM6 and CMTM4 on gastric cancer mesenchymal cells and epithelial cells predicts a poor prognosis and affects the effect of PD-1/PD-L1 immunotherapy." (PMID 36698778, 2022).
oral squamous cell carcinoma (9 papers, 2020 to 2025). "A recent study showed that CMTM6 expression was positively associated with M2-like macrophage infiltration in oral squamous cell carcinoma." (PMID 33552963, 2020). "Unbiased global proteome profiling of sensitive, early, and late cisplatin-resistant oral squamous cell carcinoma (OSCC) lines identified CMTM6 as a top-ranked upregulated protein." (PMID 33434185, 2021). "At present, only one report exists with respect to the presence of CMTM6 in exosomes; in this report, it was determined that tumor-cell-secreted exosomal CMTM6 induced M2-like macrophage polarization and contributed to malignant progression in oral squamous cell carcinoma." (PMID 39335098, 2024). "Additionally, there was a positive correlation between the CMTM6 expression and the infiltration of CD163+ macrophages in oral squamous cell carcinoma (OSCC)." (PMID 37726578, 2023).
non-small cell lung carcinoma (7 papers, 2020 to 2024). A group of at least three distinct histological types of lung cancer, including non-small cell squamous cell carcinoma, adenocarcinoma, and large cell carcinoma. "The study aimed to elucidate this ambiguity by investigating CMTM6's role in non-small cell lung cancer (NSCLC) prognosis." (PMID 38495487, 2024). "CMTM6 is expressed in advanced non-small-cell lung cancer cells and stromal cells, especially CD68-positive macrophages." (PMID 33818637, 2021). "CMTM6 expression has previously been demonstrated as a promising biomarker that is useful for PD-1/PD-L1 inhibitor therapeutic decision-making in non-small-cell lung cancer." (PMID 33818637, 2021). "Another study found the expression of CMTM6 mainly on CD68 positive macrophages in the non-small-cell lung cancer (NSCLC), and its expression is correlated with longer overall survival in the patients with immunotherapy." (PMID 34680324, 2021). "CMTM6 expression was positively correlated with PD-L1 in immunohistochemical and mRNA expression data of non-small cell lung cancer." (PMID 32874775, 2020). "Although the expression of both CMTM6 and PD-L1 is induced by related immunoregulatory factors, a previous report indicated that in advanced-stage non-small-cell lung cancer, the proportion of CMTM6-high/PD-L1+ cells is low, and some cases with PD-L1− contain high expression of CMTM6." (PMID 32770259, 2021). "In addition, a recent study showed that high expression of both CMTM6 and PD-L1, particularly in stromal ICs (CD68 + macrophages) of non-small-cell lung cancer, might identify the patients with the greatest benefit from PD-1 axis blockade." (PMID 33818637, 2021).
triple-negative breast carcinoma (7 papers, 2021 to 2025). An invasive breast carcinoma which is negative for expression of estrogen receptor (ER), progesterone receptor (PR), and human epidermal growth factor receptor 2 (HER2). "For CMTM6, a positive association similar to that recently reported for triple-negative breast cancer is likely." (PMID 39630300, 2024). "Another circUBR5 was recently reported (2024) to promote ribosome biogenesis and docetaxel resistance in triple-negative breast cancer via the miR-340-5p/CMTM6/c-MYC axis." (PMID 40806254, 2025). "Our study is aimed at investigating the expression of CMTM6 and PD-L1 proteins in triple-negative breast cancer and their correlation with the clinical pathological data of patients." (PMID 35845949, 2022). "In our study, we detected the expression of CMTM6 and PD-L1 in triple-negative breast cancer, analyzed their relationship with clinicopathological characteristics, and explored the clinical significance of CMTM6 and PD-L1 in triple-negative breast cancer." (PMID 35845949, 2022). "With the increase of TNM stage, the expression of CMTM6 and PD-L1 in triple-negative breast cancer patients also increased." (PMID 35845949, 2022). "In TIMER database, we found a positive correlation between the expression of CMTM6 and PD-L1 in triple-negative breast cancer." (PMID 35845949, 2022). "The study of CMTM6 and PD-L1 in the pathogenesis of triple-negative breast cancer requires further research." (PMID 35845949, 2022). "Our study found that CMTM6 is also highly expressed in triple-negative breast cancer." (PMID 35845949, 2022). "Our research in triple-negative breast cancer showed that CMTM6 was not an independent risk factor for triple-negative breast cancer." (PMID 35845949, 2022). "In addition to CMTM6, our in silico data on triple negative breast cancer patients showed a positive correlation between EMT markers and two other members of CMTM family (CMTM3 and CMTM7)." (PMID 33803139, 2021). "Moreover, in triple-negative breast cancer (TNBC), circ-0000512 has been revealed to inhibit PD-L1 ubiquitination by sponging the miR-622/CMTM6 axis, thus promoting TNBC progression and immune escape." (PMID 37726578, 2023).
glioblastoma (6 papers, 2020 to 2024). The most malignant astrocytic tumor (WHO grade IV). "In a separate glioblastoma study, high CMTM6 expression was identified as a potential predictor for poor prognosis with reduced survival time." (PMID 38542462, 2024). "Our results revealed that CMTM6 mRNA expression was associated with PD-L1 protein expression in BRCA, CESC, CHOL, glioblastoma multiforme (GBM), HNSC, KIRP, sarcoma (SARC), STAD, and uterine carcinosarcoma (UCS)." (PMID 33552963, 2020).
lung adenocarcinoma (6 papers, 2020 to 2024). A carcinoma that arises from the lung and is characterized by the presence of malignant glandular epithelial cells. "High expression of CMTM6 in lung adenocarcinoma has been reported as a novel independent poor prognostic factor closely related to the tumor microenvironment." (PMID 39335098, 2024). "TCGA combined with the GTEx database further confirmed the high CMTM6 expression in lung adenocarcinoma and low expression in paracancerous tissues." (PMID 36643629, 2023). "In this study, we found a significant difference in CMTM6 expression between lung adenocarcinoma and adjacent tissues." (PMID 36643629, 2023). "To further explore the expression of CMTM6 in lung adenocarcinoma, we extracted the LUAD mRNA expression in TCGA database." (PMID 36643629, 2023). "However, the role of CMTM6 is still unclear in lung adenocarcinoma (LUAD)." (PMID 36643629, 2023). "However, in lung adenocarcinoma, there is no report on the relationship between CMTM6 and PD-L2, HAVCR2 and CD200R1." (PMID 36643629, 2023). "That is, when patients with lung adenocarcinoma have high CMTM6 expression, the use of these chemotherapy drugs may not be effective, however, this findings still need to be verified by a large number of clinical cases." (PMID 36643629, 2023).
acute myeloid leukemia (5 papers, 2020 to 2024). Acute myeloid leukemia (AML) is a group of neoplasms arising from precursor cells committed to the myeloid cell-line differentiation. "In addition to the solid tumor-derived cell models, we also observed reduced CD58 expression upon CMTM6 knockout in B cell lymphoma cells (BJAB and Ramos) and acute myeloid leukemia cells (OCI-AML2)." (PMID 37683639, 2023). "Finally, pan-cancer analysis indicated that CMTM6 expression was closely related to overall survival in adrenocortical carcinoma, GBM, acute myeloid leukemia, liver hepatocellular carcinoma, mesothelioma, SARC, thymoma, and uveal melanoma." (PMID 33552963, 2020). "To investigate the roles of CMTM6 and CD58 in the antitumor T cell response in vivo, we used an in vivo xenograft model with acute myeloid leukemia (AML) cells treated with CAR-T cells." (PMID 37683639, 2023).